CDK1 (cyclin dependent kinase 1)
Diseases named in the same sentence as CDK1 in open-access papers (continued):
Sharing a sentence is not in itself a finding about the gene and the disease.
psoriasis (6 papers, 2018 to 2025). An autoimmune condition characterized by red, well-delineated plaques with silvery scales that are usually on the extensor surfaces and scalp. "CDK1 expression was increased in patients with psoriasis (versus control group) (p < 0.01), but decreased significantly after oxymatrine treatment (vs. before treatment) (p < 0.05)." (PMID 35721124, 2022). "In patients with psoriasis, the expression of CDK1 was widely distributed in all layers of the epidermis." (PMID 35721124, 2022). "Indirubin, an inhibitor of CDK1, has been reported to treat psoriasis effectively in several studies." (PMID 30341238, 2018). "Further animal experiments demonstrated that CD274 could serve as one of the effector molecules of indirubin, a CDK1 inhibitor, against psoriasis." (PMID 30341238, 2018). "Similarly, NOX4, CDK5, FLT3, ER‐α, and CDK1 are targets for psoriasis treatment." (PMID 41323822, 2025). "Related research has found that the cell cycle is significantly shortened in patients with psoriasis and that high expression of CDK1 and CCNB1 promotes keratinocyte proliferation observed in psoriasis." (PMID 35721124, 2022). "Importantly, among the DEGs, the proliferation-related genes, such as CDK1 and CCNB1, are likely important targets for treating psoriasis by oxymatrine." (PMID 35721124, 2022). "CDK1 and CCNB1 may be important targets of oxymatrine in the treatment of psoriasis." (PMID 35721124, 2022). "Moreover, the changes in DEGs represented by CDK1 and CCNB1 expression may be important biomarkers for oxymatrine efficacy in the treatment of psoriasis." (PMID 35721124, 2022).
esophageal adenocarcinoma (5 papers, 2015 to 2025). A malignant tumor with glandular differentiation arising predominantly from Barrett mucosa in the lower third of the esophagus. "In precursor lesions and esophageal adenocarcinoma, the expression of CDC72/CDK1 serves as a diagnostic and cancer progression marker." (PMID 25997441, 2015).
invasive breast carcinoma (5 papers, 2016 to 2022). A carcinoma that infiltrates the breast parenchyma. "Previously, based on invasive breast carcinomas of all intrinsic subtypes, we have reported 8.4-fold increased risk of mortality associated with the combination of separase, securin and cdk1, each a crucial regulator of cell cycle-progression." (PMID 36261751, 2022). "Moreover, the significance of this observation is reiterated by our finding that PLK1 and the FOXC2 potential target CDK1 mRNA collectively predict poor DRFS among invasive breast cancer patients after taxane-anthracycline chemotherapy." (PMID 27064522, 2016). "To investigate the clinical significance of the upstream (PLK1) and downstream (CDK1) modulators of FOXC2, we analyzed the data from a cohort of patients with invasive breast cancers following taxane-anthracycline chemotherapy." (PMID 27064522, 2016).
laryngeal squamous cell carcinoma (5 papers, 2016 to 2025). A squamous cell carcinoma that arises from the larynx. "Recently, some bioinformatics studies have identified CDK1 as a pivotal gene associated with laryngeal squamous cell carcinoma, and the CDK1 gene is closely associated with malignant progression and poor outcome of tumors." (PMID 38967843, 2024). "In addition, we also note that some bioinformatics studies have identified CDK1 as a pivotal gene associated with laryngeal squamous cell carcinoma, and the CDK1 gene is strongly associated with malignant progression and poor outcome of tumors." (PMID 38967843, 2024). "The observed upregulation of CDK1 in laryngeal squamous cell carcinoma has encouraged us to analyze for genetic mechanisms that can be responsible this phenomenon." (PMID 26912061, 2016). "In the current study, we have analyzed the expression pattern of group of genes —CCNB1, CCNB2, CCNA2, and CDK1 in laryngeal squamous cell carcinoma." (PMID 26912061, 2016). "In this study, we analyzed the expression profile of four genes (CCNA2, CCNB1, CCNB2, and CDK1) in laryngeal squamous cell carcinoma (LSCC) cell lines and tumor samples." (PMID 26912061, 2016). "Here, we have analyzed a potential target for an inhibition therapy—CDK1 in larynx squamous cell carcinoma (LSCC) and show its overexpression in this tumor." (PMID 26912061, 2016).
liver disease (5 papers, 2020 to 2026). "Pharmacological CDK1 inhibition attenuated fibrocystic liver disease in vivo." (PMID 42305588, 2026). "Likewise, peoniflorin (from Paeonia lactiflora) targeting CDK1 demonstrates various effects on liver diseases." (PMID 37108370, 2023). "In this setting, p21Cip1/Waf1 negatively regulates CDK1, and therefore increased levels of p21Cip1/Waf1 in liver disease may correlate with reduced activity of CDK1." (PMID 32578019, 2020).
metastatic melanoma (5 papers, 2015 to 2024). A melanoma that has spread from its primary site to another anatomic site. "Moreover, CDK1 plays an important role in the microenvironment of metastatic melanoma by regulating the tumor infiltration of immune cells." (PMID 35906389, 2022). "Indeed, we observed that MELK, as well as CDK1, is significantly overexpressed in metastatic melanoma." (PMID 33431809, 2021). "Most importantly, the absence of documentation of the examined molecular markers, such as BRAF, c-KIT, and CDK1, should not disorient readers from the importance of immunotherapeutic agents in metastatic melanoma." (PMID 39553047, 2024). "Notably, the top 20 genes from topological analysis algorithms included four hub genes: CDK1, FOXM1, KIF11, and RFC4, which may involve in the development of metastatic melanoma." (PMID 35906389, 2022).
renal cell carcinoma (5 papers, 2017 to 2022). "p21Cdkn1a mediates G1 arrest by inhibiting CDK1 and CDK2 and loss of CDKN1A is a predictor of poor outcome in renal cell carcinoma." (PMID 35401501, 2022). "A previous study found that 10 cell proliferation genes, including BUB1, CCNB2, and CDK1, could act as indicators for response to immune checkpoint inhibitors in PD-L1 negative renal cell carcinoma." (PMID 34440557, 2021).
renal clear cell carcinoma (5 papers, 2018 to 2024). "The upregulation of CDK1 was associated with poor survival in patients with renal clear cell carcinoma." (PMID 33178832, 2020). "HNRNPD can participate in cellular physiology, including the cell cycle and apoptosis, and plays roles in clear cell renal cell carcinoma (ccRCC) by modulating circRNA biogenesis and the mRNA levels of key genes, such as CDK1." (PMID 39180763, 2024). "To further explore the relationship between NCAPG and CDK1, we explored the effects of CDK1 on the proliferation of renal clear cell carcinoma." (PMID 35601741, 2022). "And we analyzed the correlation between NCAPG and CDK1 by immunohistochemical staining among the 72 cases with renal clear cell carcinoma; the results showed that NCAPG is related with CDK1." (PMID 35601741, 2022). "GraphPad was used for data analysis, and t-test and χ2 analysis were used to analyze the correlation between NCAPG/CDK1 and renal clear cell carcinoma." (PMID 35601741, 2022). "As a result, the role of CDK1 in renal clear cell carcinoma still remained unclear, and the relationship between NCAPG and CDK1 in renal clear cell carcinoma needs further exploration." (PMID 35601741, 2022). "Further, we explored the effects of knockdown CDK1 on the proliferation and progression of renal clear cell carcinoma; CCK-8 assay and colony forming assay were performed to observe the change of proliferation ability in HTB-47 and CRL-1932 cells." (PMID 35601741, 2022). "In summary, we preliminary proposed that NCAPG promoted the proliferation of renal clear cell carcinoma via mediating CDK1; however, the conclusion needs further verification and consolidation." (PMID 35601741, 2022). "The results consolidated the hypothesis that NCAPG promotes the proliferation and progression of renal clear cell carcinoma via mediating CDK1." (PMID 35601741, 2022). "NCAPG/CDK1 complex might provide a new treatment strategy for lots of patients with renal clear cell carcinoma." (PMID 35601741, 2022). "NCAPG might promote the proliferation of renal clear cell carcinoma via mediating CDK1." (PMID 35601741, 2022). "We further found that the expression of CDK1 was upregulated in renal clear cell carcinoma compared with normal tissue, and the expression of NCAPG was associated tightly with overall survival and disease-free survival in renal clear cell carcinoma, which was consistent with the results of NCAPG." (PMID 35601741, 2022). "The main purpose of this study is to preliminarily explore the correlation between renal clear cell carcinoma and NCAPG and CDK1." (PMID 35601741, 2022). "To further explore the correlation between CDK1 and NCAPG in renal clear cell carcinoma, we extracted the correlation between NCAPG and CDK1 from online database, and the results showed that CDK1 was positively related with NCAPG (R = 0.73; P < 0.01)." (PMID 35601741, 2022). "The next aim of our study is to explore the specific relationship between NCAPG and CDK1; the effects of NCAPG/CDK1 complex on the invasion and progression of renal clear cell carcinoma will be the next direction." (PMID 35601741, 2022). "And knockdown NCAPG could significantly restrain the proliferation and progression, NCAPG was tightly related with CDK1, and NCAPG/CDK1 complex might be the internal mechanism of NCAPG promoting the proliferation of renal clear cell carcinoma." (PMID 35601741, 2022). "Finally, we have reasons to believe that NCAPG promoted the proliferation and progression of renal clear cell carcinoma via mediating CDK1, and NCAPG/CDK1 complex might provide a new strategy for the treatment of renal clear cell carcinoma." (PMID 35601741, 2022).
urothelial carcinoma (5 papers, 2019 to 2025). A malignant neoplasm derived from the transitional epithelium of the urinary tract (urinary bladder, ureter, urethra, or renal pelvis). "Furthermore, the SLC14A1 gene is also considered a novel tumor suppressor for urothelial carcinoma, and in PCa, the downregulation of its expression promotes tumor progression by activating the CDK1/CCNB1 and mTOR pathways and is closely associated with biochemical recurrence (BCR) of PCa." (PMID 40260298, 2025). "By contrast, urothelial carcinomas subtypes with a poor prognosis display high expression of late cell cycle genes, including CDK1/cyclin B complex and its activators such as CDC25 family genes, and genes related to chromosome segregation and cell division such as BUB1, CDC20, and CENP." (PMID 31709755, 2020).
bladder (4 papers, 2015 to 2025). "Recently, we reported that overexpression of transcription factor CP2-like protein-1 (TFCP2L1) and its phosphorylation at Thr177 by cyclin-dependent kinase-1 (CDK1) play key roles in regulating bladder carcinogenesis." (PMID 35729325, 2022).
bladder tumor (4 papers, 2020 to 2022). "Down-regulation of PVT1 (an lncRNA which increases expression of CDK1) has led to lessening of bladder tumor size, decrease in the proliferation rate of tumor cells and reduction of CDK1 and Ki-67-expressing cells as demonstrated by immunohistochemistry." (PMID 36266723, 2022). "Consistent with the expression of ID2, the CDK1 transcript level was dependent on tumor grade in BC, and CDK1 was upregulated in high-grade bladder tumors." (PMID 35729325, 2022). "By contrast, p‐TFCP2L1 and CDK1 were expressed in 92.8 and 93.0% of the bladder tumor samples, respectively, with a wide range of H‐scores (0.0–231.0 with a median of 87.7 for p‐TFCP2L1, and 0.0–291.0 with a median of 100.0 for CDK1)." (PMID 31709755, 2020). "The expression of CDK1 was higher in bladder tumors than in normal urothelial tissues." (PMID 35729325, 2022). "In human bladder tumors, the expression of ID2 and CDK1 is inversely related, and the combination of low ID2 and high CDK1 expression is associated with unfavorable clinical characteristics, including high tumor grade and muscularis propria invasion." (PMID 35729325, 2022). "Next, we examined the expression levels of p‐TFCP2L1 and CDK1 and their co‐expression in normal urothelium of the urinary bladder and in a tissue microarray (TMA) construct generated from transurethral resections of bladder tumor (TURBT) specimens from 400 patients at our institute." (PMID 31709755, 2020).
brain tumor (4 papers, 2020 to 2024). "Furthermore, ongoing trials aim to evaluate the inhibition of checkpoint kinases (e.g., CDK4/6, CDK1/2) alone or in combination with CT drugs in brain tumors including recurrent and refractory SHH, Group 3/Group 4 MBs (NCT02255461, NCT04023669)." (PMID 32164294, 2020).
cyst (4 papers, 2019 to 2023). A sac-like closed membranous structure that may be empty or contain fluid or amorphous material. "Importantly, the loss of Cdk1 reduced cyst growth in a Pkd1 mutant kidney, making the Cdk1 pathway a strong candidate for the CDCA." (PMID 35253003, 2022). "Cluster 7 was annotated as proliferating cholangiocytes given its high G2/M cell cycle score and expression of BRCA2, CDC6 and CDK1 in both monolayer and cyst cells." (PMID 34764255, 2021). "Growth-promoting cell cycle checkpoint proteins (phosphorylated retinoblastoma, cdk1, cdc25C) were decreased and the inhibitory cell cycle protein p27 was increased by the combination of cyst(e)inase and auranofin." (PMID 31231686, 2019). "Additionally, genes differentially expressed only in the P70 pre-cystic data set were enriched for other pathways characteristic of ADPKD pathogenesis, including upregulation of cell cycle and Cdk1, a known driver of cyst proliferation in ADPKD." (PMID 37217845, 2023). "Furthermore, enrichment of differentially expressed genes unique to the pre-cystic data set were also Cdk1 pathway members which, in particular, have been indicated as a critical driver of cyst proliferation in ADPKD." (PMID 37217845, 2023).
endometriosis (4 papers, 2020 to 2025). The growth of functional endometrial tissue in anatomic sites outside the uterine body. "Assessment of the RNA interaction network in endometriosis has resulted to identification of the role of miRNAs and lncRNAs that are associated with cyclin-dependent kinase 1 (CDK1) and proliferating cell nuclear antigen (PCNA)." (PMID 32850438, 2020). "Evaluation of the RNA interaction network in endometriosis has revealed the role of miRNAs and lncRNAs associated with growth and apoptosis genes regulation in endometrial stromal cells, namely, Cyclin-Dependent Kinase 1 (CDK1) and Proliferating Cell Nuclear Antigen (PCNA)." (PMID 40792071, 2025).
gastrointestinal stromal tumor (4 papers, 2015 to 2025). "In gastrointestinal stromal tumor, CDK1 is associated with a shorter period of disease-free survival." (PMID 25849598, 2015). "CDK1 also shows high expression in gastrointestinal stromal tumor(GIST)." (PMID 40748969, 2025). "CDK1 is reported to be highly expressed in late‐stage gastrointestinal stromal tumors but not in early‐stage gastrointestinal stromal tumors." (PMID 38071755, 2023).
HCMV infection (4 papers, 2014 to 2020). "Maintaining CDK1/2 activity has been reported as essential for successfully establishing latent HCMV infection." (PMID 27824944, 2016). "The activation of Cdk1 by HCMV infection could result in the fragmentation of the Golgi membrane ribbon via phosphorylation of Grasp proteins, as has been described during cell division (37, 41, –, 43, 48)." (PMID 27703074, 2016). "Therefore, to gain further insights into HCMV-induced SAMHD1 phosphorylation, we next asked whether Cdk1/2 were involved in T592 phosphorylation in response to HCMV infection, since cellular cyclin A2/Cdk1/2 complexes have been shown to phosphorylate SAMHD1 at T592." (PMID 32986788, 2020). "According to this model, HCMV infection stimulates IER5 expression, which in turn inhibits CDC25B expression and CDC25B-dependent CDK1 activation, contributing to IE1 transcription and lytic viral replication." (PMID 27824944, 2016). "However, we observed a high proportion of CDK1 in the nuclear fraction of UL21a-RXL2mut-infected cells, suggesting that Cyclin A2 down-regulation by pUL21a is also responsible for the limited nuclear availability of this essential mitotic kinase during HCMV infection." (PMID 25393019, 2014). "The failure of CDK1 WT to inhibit IE1 expression at a late stage of HCMV infection likely resulted from the lack of CDC25B activity, correspondingly reducing the activation of CDK1 WT." (PMID 27824944, 2016). "Furthermore, CDK1 WT failed to suppress HCMV IE1 expression during late stages of HCMV infection." (PMID 27824944, 2016).
laryngeal carcinoma (4 papers, 2016 to 2025). Carcinoma that arises from the laryngeal epithelium. "Through bioanalysis of survival-related genes in laryngeal cancer patients, we discovered that CDK1 expression is related to the survival rate of laryngeal cancer patients and is probably a therapeutic target for laryngeal cancer." (PMID 38967843, 2024). "This study suggests that targeting lncRNA FLJ20021 can be a promising approach to combat cisplatin resistance in laryngeal cancer by regulating CDK1 and promoting PANoptosis via the ZBP1 pathway." (PMID 38967843, 2024). "The role of CDK1 protein overexpression in surgery margins of laryngeal cancer was noticed by Yang and coworkers who had shown its relation with the local relapse occurrence." (PMID 26912061, 2016). "Therefore, we targeted CDK1 as a candidate downstream target gene of lncRNA FLJ20021 in laryngeal cancer." (PMID 38967843, 2024). "Moreover, the involvement of CDK1 in tumorgenesis was postulated in various types of cancer, including laryngeal cancer." (PMID 26912061, 2016). "Moreover, a group of other microRNAs was identified as potentially involved in the regulation of CDK1 gene in laryngeal cancer." (PMID 26912061, 2016). "Therefore, we speculate that CDK1 may be a key regulatory target that mediates PANoptosis and participates in cisplatin resistance in laryngeal cancer." (PMID 38967843, 2024). "A recent study in laryngeal cancer demonstrated that FLJ20021 predominantly localizes to the nucleus and binds CDK1 mRNA, enhancing its stability." (PMID 40547360, 2025). "lncRNA FLJ20021 is highly expressed in cisplatin-resistant laryngeal cancer cells, and silencing lncRNA FLJ20021 plays a positive role in overcoming cisplatin-resistant laryngeal cancer by regulating CDK1 and mediating PANoptosis in a ZBP1-dependent manner." (PMID 38967843, 2024). "However, the regulatory mechanisms and key roles of CDK1 and lncRNA FLJ20021 in laryngeal cancer need to be further elucidated." (PMID 38967843, 2024). "Subsequently, sh-FLJ20021 and pcDNA 3.1 or pcDNA-CDK1 were transfected into Hep-2/R cells to determine whether CDK1 was involved in lncRNA FLJ20021-mediated PANoptosis and affected the malignant progression of laryngeal cancer and cisplatin resistance." (PMID 38967843, 2024). "However, the immunohistochemical analysis of laryngeal cancer tissue sections has revealed that the CDK1 protein is present both in cancer and non-cancer tissue samples (histopathologically normal surgical margins of laryngeal tumors)." (PMID 26912061, 2016).
lung squamous cell carcinoma (4 papers, 2021 to 2023). "Finally, CDK1, PLK1, PCNA, ZWINT and NDC80 identified as hub genes for underlying molecular mechanisms of lung squamous cell carcinoma and lymphatic metastasis." (PMID 37185598, 2023). "Finally, CDK1, PLK1, PCNA, ZWINT and NDC80 identified as hub genes for underlying molecular mechanisms of lung squamous cell carcinoma lymphatic metastasis." (PMID 37185598, 2023).
malaria (4 papers, 2011 to 2021). Malaria is a serious and sometimes fatal disease caused by a parasite that commonly infects a certain type of mosquito which feeds on humans. "While Cdk1 is essential in yeast and mammals, deletion of PbPK5 (the PfPK5 homolog) in the mouse malaria Plasmodium berghei does not result in a detectable phenotype." (PMID 28611247, 2017).